MMP2 (matrix metallopeptidase 2)
Diseases named in the same sentence as MMP2 in open-access papers (continued):
Sharing a sentence is not in itself a finding about the gene and the disease.
myopia (continued). "For example, matrix metalloproteinase-2 (MMP-2) is a scleral extracellular matrix degradation enzyme, and its activation induces collagen fiber I degradation, followed by loss of scleral connective tissue, together with scleral thinning and weakening, which leads to axial elongation and myopia." (PMID 36031679, 2022). "Elevated levels of these cytokines in the retina and sclera have been observed in myopia models, where they upregulate MMP-2 expression and promote collagen I degradation, thereby contributing to scleral remodeling and progression of myopia." (PMID 41222199, 2025). "MMP2 mediates extracellular matrix degradation, promoting scleral thinning and axial elongation – hallmarks of myopia." (PMID 40749709, 2025). "Activation of MMP-2 expression in the retina leads to collagen cleavage, scleral remodeling, and finally myopia." (PMID 41191163, 2025). "The potential to modulate SHH activity presents a promising therapeutic target for managing myopia by controlling the overexpression of MMP-2 and managing the structural changes in the eye that lead to myopia." (PMID 40933557, 2025). "The abnormal expression of matrix metalloproteinase-2 (Mmp2) and interleukin-6 (Il6) can induce myopia, and these are regulated by NF-κB (Libermann and Baltimore, 1990; Wu and Schmid-Schönbein, 2011)." (PMID 40864167, 2025). "Upregulated IL-6 activated the TGF-β1/Smad2/MMP-2 pathway and promoted transdifferentiation of human scleral fibroblasts, resulting in sclera thinning and myopia progression." (PMID 41224847, 2025). "The C-C motif chemokine ligand-2 (CCL2) can recruit monocytes to differentiate into macrophages, and the infiltrating macrophages express high levels of MMP-2, which promotes myopia progression." (PMID 40909333, 2025). "During myopia progression, matrix metalloproteinase-2 (MMP-2), a key enzyme upregulated in scleral remodeling, promotes degradation of the extracellular matrix." (PMID 41302167, 2025). "In myopia, MMP-2 degrades collagen and other ECM components in the sclera, which is essential for the dynamic remodeling of this tissue." (PMID 40933557, 2025). "Activation of the PI3K/AKT pathway regulates factors like TIMP-2 and MMP-2, which are involved in scleral remodeling and affect the axial length of the eye, contributing to myopia progression." (PMID 40933557, 2025). "After 2- and 4-week myopia induction, the MMP2 and TIMP2 expression in scleral tissues in the right eyes from the NC and LIM groups were detected by ELISA." (PMID 40216914, 2025). "MMP2 and TIMP2 have long been associated with myopia and our previous data showing that their distribution was changed after dark-rearing." (PMID 39607017, 2024). "Animal model studies on myopia have demonstrated that increased expression of MMP-2 correlates with reorganization of the scleral structure and ECM remodeling 9,10." (PMID 39430251, 2024). "Levels of DKK1 and MMP-2 were significantly higher in the pathologic myopia group than in the low-to-moderate myopia and control groups." (PMID 39597899, 2024). "The VEGF concentration in the aqueous humor factor was negatively correlated with the AL in the myopia group (r = −0.438, p = 0.002), the MMP-2 concentration was positively correlated with the AL (r = 0.484, p = 0.010)." (PMID 39086954, 2024). "The levels of Dickkopf 1 (DKK1) and matrix metalloproteinase 2 (MMP-2) in the vitreous humor of patients with myopia." (PMID 39597899, 2024). "Studies have shown that prolonged inflammation can exacerbate myopia by enhancing the expression of inflammatory components such as MMP-2, TGF-β, IL-1β, IL-6, and TNF-α." (PMID 39006849, 2024). "The results of this study showed that the MMP-2 concentration in aqueous humor increased in the high myopia group compared with the emmetropia group and was positively correlated with the AL." (PMID 39086954, 2024).
myopia (continued). "In summary, RT, blood flow density and visual function are impaired in patients with high myopia, while our findings suggest a potential association between concentrations of VEGF and MMP-2 in the aqueous humor and the development of high myopia." (PMID 39086954, 2024). "Compared to the experimental eyes of mice injected intraperitoneally with saline, those injected with MCC950 showed a reduced degree of myopia shift, lower expression levels of MMP-2, and higher expression of Collagen-1." (PMID 37958819, 2023). "A similar situation occurred in LIM tree shrews; when myopia is induced, the mRNA level of MMP2 increases significantly and subsequently decreases in the recovery period." (PMID 37907982, 2023). "In the FDM model of tree shrews, an exogenous tissue inhibitor of metalloproteinase 2, which is an endogenous inhibitor of MMP2, inhibited the development of myopia." (PMID 37907982, 2023). "Oral native-LF has been shown to be effective in downregulating MMP-2 expression in the sclera to suppress the progression of myopia." (PMID 36982888, 2023). "Meanwhile, the progression of myopia produces more MMP-2, promoting further release of inflammatory factors and ultimately creating a malignant cycle." (PMID 37849748, 2023). "It is also shown that the protein level of MMP-2 was decreased by whole-body UVA irradiation plus oral administration of riboflavin in the guinea pig model of lens-induced myopia." (PMID 36652495, 2023). "An increase in MMP-2 expression has also been found in the aqueous humor and vitreous specimens from human patients with high myopia." (PMID 36652495, 2023). "The TIMP-4 efficiently inhibits the activity of MMP-2 via its N-terminus, and MMP2 upregulation was accompanied by significant myopia." (PMID 38069250, 2023). "To confirm which signaling pathway is involved in the progression of myopia, we performed immunohistochemistry to determine the levels of MMP2, COL-1, and NF-κB." (PMID 36135208, 2022). "The upregulation of MMP2 expression promotes the development of myopia via the cleaving of scleral collagen, degradation of the extracellular matrix, and reduction of scleral biomechanics." (PMID 36451140, 2022). "Previous studies have shown that TGF-β is downregulated in the context of scleral tissues with myopia and associated with ECM degradation and fibroblast transformation via the increase in levels of MMP2 or α-SMA." (PMID 36261846, 2022). "MMP-2, which is a kind of zinc-dependent protease, can degrade the extracellular matrix of the sclera and mediate scleral remodeling in experimental myopia." (PMID 34001063, 2021). "MMP2 has also been shown to be upregulated in the sclera of chicks and tree shrews, by form deprivation-induced myopia." (PMID 34287272, 2021). "Evidence from animal models of myopia in chicks and tree shrews showed that the MMP-2 expression is upregulated in the sclera." (PMID 34285659, 2021). "In animal models of myopia such as tree shrews, chicks, Guinea pigs, and mice, MMP-2 is significantly upregulated." (PMID 32596291, 2020). "The upregulation of MMP2 in the sclera during the myopia process contributed to the degradation of the collagen and elongation of the eye length." (PMID 32719611, 2020). "MMP-2 upregulation was shown to precede myopia development, whereas reduced expression of the tissue inhibitor of metalloproteinase was associated with myopia development." (PMID 30665391, 2019). "For example, the two key indicators for myopia development, the vitreous chamber depth and spherical-equivalent refractive error, showed moderate correlations with the mRNA levels of MMP2 and TIMP2 genes in the superior scleral." (PMID 28900109, 2017). "Suppression of scleral fibroblast and RPE cell expression and secretion of MMP-2 by miR-29a can be used as a therapeutic target for the prevention and treatment of myopia." (PMID 28630860, 2017).
myopia (continued). "Increased scleral MMP-2 expression in form-deprivation myopia has been shown in tree shrews at the protein and mRNA levels and in guinea pigs at the protein level." (PMID 28630860, 2017). "Some modulators, including matrix metalloproteinase (MMP)-2, are upregulated in the sclera in experimental myopia." (PMID 24810957, 2014). "Upregulation of MMP-2 expression was reported to be essential for scleral remodeling in experimental myopia in previous studies." (PMID 24810957, 2014). "Complete sequencing of the coding regions and the adjacent intronic regions of MMP2 in the 200 subjects with high myopia and 200 normal controls identified seven variations." (PMID 23378725, 2013). "An increased MMP2 transcript level has also been found in human scleral fibroblasts mechanically stretched in an in vitro system and in lens-induced myopia in the tree shrew." (PMID 23378725, 2013). "MMP2 is increased in the sclera of the eye with myopia induced by form deprivation in chicks when compared with the control eye." (PMID 23378725, 2013). "In conclusion, we genotyped 20 SNPs at the MMP2 gene in a Han Chinese group composed of 400 patients with high myopia and 400 controls." (PMID 23378725, 2013). "The purpose of this study was to examine the relationship between high myopia and MMP2 in a mainland Han Chinese population." (PMID 23378725, 2013). "First, we used a case-control study approach to examine the relationship between high myopia and the tag SNPs of MMP2 in a mainland Han Chinese population." (PMID 23378725, 2013). "Matrix metalloproteinase 2 (MMP2) has been shown to be expressed in the human sclera, and is increased in the sclera of the eye with myopia induced by form deprivation in chicks when compared with the control eye." (PMID 23378725, 2013). "When the coding regions and the adjacent intronic regions of MMP2 in the 200 subjects with high myopia and the 200 normal controls were completely sequenced, one novel variation and six known variations were detected." (PMID 23378725, 2013). "Increased scleral MMP2 expression in form-deprivation myopia has been shown in tree shrews at the protein and the messenger RNA (mRNA) levels and in guinea pigs at the protein level." (PMID 23378725, 2013). "Screening for mutations in the coding regions and the adjacent intronic regions of MMP2 was performed in 200 patients with high myopia and 200 normal controls by direct sequencing." (PMID 23378725, 2013). "Seven variations were detected upon sequencing of the coding regions and the adjacent intronic regions of MMP2 in 200 subjects with high myopia and 200 normal controls." (PMID 23378725, 2013). "During the development of visual deprivation myopia, the expression level of MMP-2 in the scleral fiber layer of chickens was elevated compared with that of normal controls, while the expression level of TIMP-2 was decreased compared with that of normal controls." (PMID 40375931, 2025). "In addition, the expression levels of myopia-related factors, such as Tgfβ1, Mmp2, and Il6, were upregulated in the retina and sclera of the Zc3h11a+/- mice." (PMID 40864167, 2025). "Research into MMP-2 inhibitors or other compounds that modulate MMP-2 activity in the eye could provide new treatment options for myopia." (PMID 40933557, 2025). "A LIM study showed that LF and its hydrolysates significantly reduced IL-8, MMP-2, and NF-κB levels, suggesting that LF may delay myopia progression by attenuating inflammation." (PMID 41191163, 2025). "Bridging molecular insights (e.g., hypoxia-HIF-1α-MMP-2 axis) with innovations like gene editing is essential to curb myopia progression, necessitating prioritized research on multiple pathways interaction and translational trials to advance precision ocular therapies." (PMID 40933557, 2025). "Since changes in myopia are mainly associated with changes in the posterior pole, this may result in a less pronounced relationship between VEGF or MMP-2 and high myopia." (PMID 39086954, 2024).
myopia (continued). "When the MMP-2 concentration in the aqueous humor increases, it may be developing into high myopia, and relevant measures should be taken in time for prevention." (PMID 39086954, 2024). "Increased MMP-2 expression and activity are observed in both mammalian and avian models of myopia." (PMID 36652495, 2023). "MMP2 appears to be closely related to myopia and degradation of ECM." (PMID 37907982, 2023). "In addition, there is a strong positive correlation between ocular axial length and the expression levels of IL-6 and MMP-2 in patients with high myopia." (PMID 36700118, 2023). "Altered expression of MMP-2 and MT1-MMP may be one of the mechanisms underlying the protective effects of SXL in the guinea pig myopia model." (PMID 36652495, 2023). "MMP-2 significantly upregulated in myopia animal models such as tree shrews, chickens, and mice." (PMID 38069250, 2023). "As with myopia, MMP2 may also play a crucial role in modulating the scleral remodelling during ocular hypertension." (PMID 36349481, 2022). "Furthermore, in hamsters with myopia, an increased expression of MMP-2 was induced by TGF-β through NF-κB activation." (PMID 36242032, 2022). "In mice, during form-deprivation myopia, MMP-2 mRNA is elevated in a time-dependent manner." (PMID 32596291, 2020). "Furthermore, LF suppressed lens-induced myopia (LIM)-induced MMP-2 activation, besides increasing COL1A1 expression." (PMID 33291388, 2020). "Thus, LF can counteract myopia development by suppressing collagen I degradation by MMP-2 inhibition, and by enhancing collagen I synthesis in scleral fibroblasts." (PMID 33291388, 2020). "Scleral remodeling resulting in abnormal elongation of the globe is closely related to the presence of degenerative changes seen in pathologic myopia, and these changes may be reflected at the molecular level by alterations in the levels of MMP-2 and TIMP-215." (PMID 31673022, 2019). "Numerous studies on myopia have emphasized changes in MMP-2 expression in the sclera." (PMID 28630860, 2017). "During myopia development, the sclera undergoes active remodeling, which involves MMP-2." (PMID 26762140, 2016). "Taken together, these results suggest that Shh might induce myopic development by enhancing the expression and activity of MMP-2 in animal models of myopia." (PMID 24810957, 2014). "Taken together, these data suggest that the PI3K–AKT might be the upstream pathway controlling MMP-2 expression in Shh-induced experimental myopia and that PRE cells might be the source of the signal." (PMID 24810957, 2014). "In this study, thus, we sought to evaluate MMP2 as a candidate gene for high myopia." (PMID 23378725, 2013). "In this study, 20 SNPs were genotyped for MMP2, and none showed significant association with high myopia in the mainland Han Chinese population." (PMID 23378725, 2013). "The finding of higher estradiol levels in male high-myopia cases is consistent with our hypothesis that differential sex hormone levels may play a role in myopia pathogenesis by regulating MMP-2." (PMID 21921981, 2011). "Combining MMP-2 inhibition with existing treatments, such as optical corrections, atropine eye drops, and lifestyle modifications, could offer a comprehensive strategy for managing myopia." (PMID 40933557, 2025). "Elevated hypoxia-induced IL-6 has been demonstrated to exacerbate myopia by promoting scleral remodeling through the TGF-β1/Smad2/MMP-2 pathway, supporting the hypothesis that metabolic inflammation contributes to myopia through a “metabolic-immune-hypoxia” network." (PMID 41191163, 2025). "Consequently, elevated MMP-2 in myopia results from: Disrupted dopamine signaling (light exposure to D2R activation and MMP-2); Therapeutic MMP-2 inhibition (e.g., TIMP-2 gene therapy, doxycycline) synergizes with cAMP-elevating agents to preserve scleral integrity." (PMID 40933557, 2025).
myopia (continued). "Thus far, previous studies using the form-deprived myopia (FDM) animal model have demonstrated that transforming growth factor-β (TGF-β), metalloproteinase 2 (MMP2), and tissue inhibitor of metalloproteinase-2 (TIMP-2) in sclera are associated with the development of myopia." (PMID 35409006, 2022). "Therefore, it appears that elevated MMP2 activity is important and is likely involved in myopia pathogenesis, since MMP2 has collagenase and gelatinase activity, which could then lead to scleral degradation." (PMID 34698138, 2021). "In addition, brimonidine might affect the development of myopia by upregulating Col1a1 and Mmp2 gene expression in the retina." (PMID 34256866, 2021). "Furthermore, MMP-2 is a key player in scleral remodeling and myopia development." (PMID 33291388, 2020). "However, the mechanism responsible for the upregulation of MMP-2 in myopia development remains unclear." (PMID 32596291, 2020). "In conclusion, the suppression of MMP-2 expression and its secretion in scleral fibroblasts and RPE cells stimulated by miR-29a may provide a molecular basis for understanding the mechanisms underlying myopia progression." (PMID 28630860, 2017). "TGF-β2 increases matrix metalloproteinase 2 (MMP2) and decreases collagen I expression, promoting myopia." (PMID 40862775, 2025). "Further, we investigated the changes of PIK3R3, AKT2 and TGF-β1, E-cadherin, COLI, BCL-2, BAD, MMP2, and TIMP2 in the sclera of myopic guinea pigs to explore their effects on the development of myopia after 2- and 4-week myopic induction." (PMID 40216914, 2025). "We also found a significant increase in MMP2 and lower collagen 1 expression in the retina of TGF-β-treated eyes, which further confirmed the development of myopia." (PMID 40862775, 2025). "This possibility further supports the relevance of MMP2 as both a downstream effector and an upstream enhancer of TGF-β signaling, consistent with its role in scleral remodeling and myopia development." (PMID 40862775, 2025). "After myopia induction for 2 and 4 weeks, the expression of PIK3R3, AKT2, BAD, BCL-2, TGF-β1, E-cadherin, COLI, MMP2, and TIMP2 was detected by qPCR." (PMID 40216914, 2025). "Studies have demonstrated that the MMP-2 and IL6 expression levels are increased in myopic eyes and that inhibiting MMP-2 or IL6 expression will provide some degree of control over myopia progression." (PMID 40864167, 2025). "The results showed that the MMP2 expression in the sclera of guinea pigs in the LIM group was increased compared with the levels of the NC group after 2 and 4 weeks of myopia induction." (PMID 40216914, 2025). "Similar results have been validated in animal studies, where the induction of myopia leads to increased TGF-β and matrix metalloproteinase-2 (MMP-2) expression, accompanied by significant increases in IL-6, IL8, TNF-α and MCP-1." (PMID 41191163, 2025). "In conclusion, the intraperitoneal injection of MCC950 can attenuate the progression of myopia in FDM by downregulating the expression levels of NLRP3 and its downstream signaling pathway factors (IL-1β, IL-18, Caspase-1, and MMP-2)." (PMID 37958819, 2023). "A previous study showed that oral LF administration inhibited minus lens-induced myopia (LIM) development in mice by suppressing inflammation, such as increased interleukin (IL)-6 and matrix metalloprotease (MMP)-2 activity." (PMID 36982888, 2023). "MMP-2 expression preceding myopigenesis can be observed in FDM, whereas its decline can also directly impede myopia progression." (PMID 37849748, 2023). "MMP-2, which is one target of transforming growth factor (TGF) β signaling via NFκB, can cleave collagens, thereby promoting the progression of myopia." (PMID 36064391, 2022). "NF-κB can also activate the expression of MMP2 and TGF-β while downregulating COL-I expression to promote myopia progression." (PMID 36135208, 2022).